IL6 (interleukin 6)
Diseases named in the same sentence as IL6 in open-access papers (continued):
Sharing a sentence is not in itself a finding about the gene and the disease.
infection (continued). "IL-6 is a pleiotropic cytokine secreted by a variety of cells in response to various stimuli, such as infections and other cytokines, including IL-1β, interferon gamma (IFN-γ), and TNF-α." (PMID 29233145, 2017). "Results showed that IL-23, EBI-3 (IL-27 beta subunit), IL-12p40, IL-12p35, IFN-γ, IL-6, and IL-10 mRNA expression were all increased both in the liver and in the spleen during PbNK65 hrfΔ infection as compared to WT infection." (PMID 28831137, 2017). "To address the role of IL-6 in thymocyte differentiation during infection, we first analysed the mRNA gene expression of IL-6 and its receptors in the thymus." (PMID 28147332, 2017). "Cytokines such as TNF-α, IL-1β, and IL-6 play key roles in various inflammatory processes, such as the acute-phase reaction, tissue damage, and infection." (PMID 28524081, 2017). "An adequate production of pro-inflammatory cytokines such as IFN-γ, TNF-α, IL-1, IL-12, and IL-6 is essential for controlling infection by intracellular parasites." (PMID 28572772, 2017). "WT infection of PMA-treated THP-1 cells resulted in higher levels of CCL5 in the supernatant than did infection of NHDF or hAEC and higher levels of IL-6 than did infection of NHDF." (PMID 28270578, 2017). "To investigate the role of endogenous IL-6 in EV-A71 infection, we infected and compared wild-type C57BL/6J mice and C57BL/6J–derived mice with a targeted disruption of the gene encoding IL-6." (PMID 29233145, 2017). "Subsequently, infection leads to the activation of the nuclear factor-κB (NF-κB) signaling pathway and the production of pro-inflammatory cytokines, such as IL-6 and tumor necrosis factor (TNF), using innate immune cells." (PMID 28935867, 2017). "Interleukin (IL)-1β and IL-6 are both pro-inflammatory cytokines whose levels have been shown to increase within hours of infection in crticially ill patients and are inversely related to serum Ca concentrations." (PMID 28993435, 2017). "The levels of IL-1α, IL-1β, IL-6, and IL-18 were unchanged or increased in Ccr2-/- mice during infection, likely reflecting increased cytokine production by other immune cell types in response to the substantial increase in bacterial load." (PMID 28384349, 2017). "Asthmatic bronchial epithelial cells have a deficient IL-6 and CCL5 induction in response to rhinovirus-16 infection compared with cells from healthy volunteers." (PMID 28842514, 2017). "In infected mice, TFF1 is initially upregulated in gastric antrum in the acute phase of infection, along with IL-1β and IL-6." (PMID 29085807, 2017). "Although all three strains induced IL-6 production by BMDMs compared to uninfected control cells (medium), H37Rv::Δ3875 induced less IL-6 production by macrophages at 24 h and 48 h with significant reduction at 48 h post infection compared to H37Rv." (PMID 28106119, 2017). "At 7 days after infection, IL-6 was detected at significantly lower levels in BALF and lung samples from heat-killed DK128 pretreated mice than those in mock-treated mice after infection." (PMID 29234060, 2017). "Results from this cellular system showed that when the trefoil peptide is expressed, the pro-inflammatory cytokines (IL-8 and IL-6) induction upon infection is reduced." (PMID 29085807, 2017). "In the presence of infection by RH strain, untreated cells presented high IL-6 release compared to untreated and uninfected cells (P < 0.05)." (PMID 28798905, 2017). "Infection of one-day-old BALB/c mice and treatment with anti-IL-6 antibody at the time of infection reduced the viral load in the tissue (intestine) from days 1 to 7 p.i. but increased the mouse mortality rate." (PMID 29233145, 2017). "In this context, it is conceivable that the enhanced release of IL-12, TNF-α, IL-1β, and IL-6 by ΔesxB infection likely promotes a robust Th1 and Th17 response, whose crucial role in the immunity against S. aureus has been demonstrated by several studies." (PMID 28785545, 2017).
infection (continued). "Whereas IL-1β and TNF-α are the first cytokines in an infection and are generally pro-inflammatory, IL-6 is secreted thereafter and acts in both pro- and anti-inflammatory roles." (PMID 29078765, 2017). "In contrast, IL-6 levels in A(H1N1)pdm09-challenged control mice were 198.6 pg/mL at 2 days post-infection, peaked at 463.5 pg/mL by 3 days post-infection, and remained at similar levels at 7 days post-infection." (PMID 28831046, 2017). "In IL-6−/− mice, EV-A71 infection increased the numbers of CD4+ T cells and CD8+ T cells, but not the number of CD19+ B cells." (PMID 29233145, 2017). "In particular, the levels of IL-6 were upregulated up to 5.6 fold in calcitriol-treated infected mice at 4 days post-infection." (PMID 28114957, 2017). "Although a variety of studies on preprosthetic infections have shown that IL-6 was a significant independent predictor of infection, there is little knowledge about the utility of IL-6 in the diagnosis of infected nonunion." (PMID 29130050, 2017). "In this context, IL-8 and IL-6 are widely used to assess the inflammatory state in CF cells and to measure the inflammatory response of CF cells upon infection." (PMID 29282053, 2017). "In contrast, the CRP and IL-6 levels were under control in the pigs treated with Epi-1 after infection." (PMID 28177877, 2017). "Further support for many of these effects being IL-6 independent was provided by studies of permissiveness for lytic IE gene expression upon infection." (PMID 28400599, 2017). "IL-6 is a central mediator of the immediate induction of hepatic acute phase proteins (APP) in the liver during infection and after injury, but increased IL-6 activity has been associated with multiple pathological conditions." (PMID 29062282, 2017). "Animals inoculated with vital Cp and animals that acquired the infection naturally had higher amounts of IL-6 in their lavage than animals inoculated with BGM cells." (PMID 29281663, 2017). "IL-6 has previously been identified as a marker of subclinical infection in cetaceans but it is unclear if this is the case for harbor porpoises." (PMID 29272269, 2017). "The infection of microglia with P. gingivalis also significantly increased the secretion of IL-6 and TNF-α, and the accumulation of NO metabolites." (PMID 28924232, 2017). "Infection with H37Rv induced significantly higher amounts of IL-6 by both murine and human macrophages than its esat-6 deletion mutant." (PMID 28106119, 2017). "IL-6, IL-8, and IL-10 circulating levels were shown to be higher during infection and further larger studies are needed to confirm these findings." (PMID 28148470, 2017). "Especially, interleukin-6 is one of the multifunctional cytokines that control humoral immunity and are involved in inflammation, infection responses, and metabolic regulation." (PMID 29259311, 2017). "These cytokines (e.g., CCL8, FAS, and IL-6) begin to see significant expression in fatal cases starting at 4–5 days post-infection and are sustained through to the end of infection." (PMID 28930167, 2017). "We found that the levels of IL-1α, INF-γ, TNF-α, MCP-1, IL-1β, IL-10, IL-6, IL-27, and IL-17α in the lungs post infection were significantly different between alcohol- and pair-fed mice." (PMID 28604843, 2017). "Resident astrocytes are involved in CNS inflammation after trauma or infection by secreting host-cellular factors such as IL-6." (PMID 28824880, 2017). "IL-6 production induced by injury or infection is an important SOS signal that coordinates activities of liver cells, macrophages, and lymphocytes." (PMID 29201029, 2017). "TNF-α is released by macrophages in response to infection, stimulates the production of downstream cytokines, such IL-6 and IL-8, and plays a significant role in activating the cytokine cascade." (PMID 28694565, 2017).
infection (continued). "HCV induced inflammatory cytokine expression however, likely plays a small role in metallothionein induction following infection, as we demonstrated only mild metallothionein expression following interferon/IL-6 treatment." (PMID 28513591, 2017). "In T cells and macrophages, IL-6 is secreted in response to infection and acts as a pro-inflammatory cytokine." (PMID 28877226, 2017). "IL-6 transcription was significantly up-regulated during primary infection, starting at D7pi and during the course of the second BTV challenge." (PMID 28662714, 2017). "Consistent with previous studies, we also observed an increase in IL-6 levels in the severe model at the early stage of infection." (PMID 29156632, 2017). "Macrophages produce pro-inflammatory mediators in situ, such as nitric oxide (NO), TNF-α, and interleukin 6 (IL-6), that inhibit T. cruzi multiplication and differentiation, precluding the spread of the infection within the host." (PMID 29312293, 2017). "In the case of H5N1 IAV IL-6 promotes the survival of anti-viral neutrophils at the site of infection." (PMID 28953978, 2017). "Three days after the infection, expression of IL-6 was significantly increased in the S and SP groups in comparison with the NC and P groups." (PMID 28659929, 2017). "The diagnostic utility of IL-6 is inferior to CRP and the finding conflicts with previous conclusions drawn from periprosthetic infections." (PMID 29130050, 2017). "In a recent study, infection-related cytotoxic T cells stimulate interleukin-6 (IL-6) secretion from MSC and promote myelopoiesis." (PMID 28485401, 2017). "To address the significance of endogenous IL-6 in EV-A71 infection, we used two approaches by comparing infected IL-6 gene knockout mice and wild-type mice and by applying neutralizing monoclonal antibody to deplete IL-6 in wild-type mice." (PMID 29233145, 2017). "Our results showed the intestinal fluids of AKT-blocked mice produced significantly more IL-12 p40, IFN-γ, TNF-α, and IL-6 during the early stage of infection (5 dpi) compared with infected WT mice." (PMID 28979269, 2017). "The pro-inflammatory cytokine IL-6 was moderately elevated in several animals in both the aerosol and IT infection groups, but was particularly enhanced in the one animal that had nasal discharge during the aerosol exposure (#8095)." (PMID 28388650, 2017). "Analysis of mRNA levels of IL-6 and other pro-inflammatory cytokines and chemokines at 2.5 h, 4 h and 8 h post infection (p.i.) revealed a moderate induction of IL-6, TNFα, CCL3 and CCL5 upon IV infection of Calu-3 cells." (PMID 28195157, 2017). "Twenty-four hours post-infection, the mRNA levels of IL-6, IL1B, and IL-8 were lower in the testosterone-pretreated cells in a dose-dependent manner (p < 0.05) compared to those of the positive control." (PMID 28665978, 2017). "In contrast, IL-6 is usually considered to be a major cytokine which promotes inflammatory responses during infection, but we recently discovered that TLR-induced IL-6 counter-regulates antiviral CD8+ T cell response." (PMID 29218046, 2017). "Infection of H3N2 and H1N1 viruses causes the upregulation of IL-6, CXCL9, and CXCL10 in cultured human umbilical vein endothelial cells." (PMID 28399143, 2017). "During infection, the activated astrocytes generate IL-1β and IL-6 through the p38/IκB- or TNFα/NF-κB-mediated pathway and delay neuronal death in pathological situations with H2O2 generation." (PMID 28950910, 2017). "We found that the levels of IL-1α, INF-γ, TNF-α, MCP-1, and IL-6 in the lungs post infection were significantly different between mice recolonized with microbiota from alcohol-fed and pair-fed microbiota." (PMID 28604843, 2017). "We found LPS priming can recover the expression of the repressed the cytokines (TNF-α, IL-6 and IL-1β) after Ms_PE_PGRS41 infection." (PMID 28440335, 2017).
infection (continued). "Numerous studies show that IL-6 modulates various aspects of the innate immune system, such as hematopoiesis and influx of neutrophils at sites of infection or trauma." (PMID 29163240, 2017). "We measured significant levels (2 to 3-fold) of IL-1β, at 8 days up to 6 weeks post-infection, and increased IL-6 levels (ca. 5-fold) at day 5 post-infection." (PMID 29085807, 2017). "Four out of nine IL-6−/− mice continued to lose weight and died between 6 and 10 days after infection, whereas only one out of 16 WT mice lost weight without weight gain and died at day 10 post-infection (p.i.)." (PMID 28262742, 2017). "We found that the deficiency of IL-6 or IL-23 impaired the IL-17A-production, which was ~2.5 times smaller than C57BL/6 mice at the same period of infection (p < 0.05)." (PMID 28871251, 2017). "IL-6 is essential for clearance of bacteria after i.n. infection, via generation of Th17 cells; IL-6−/− mice are capable of generating a Th1 immune response to an i.n. bacterial challenge but cannot control infection." (PMID 28484451, 2017). "After 6 h of infection, we found significantly decreased levels of pro-inflammatory cytokines, including IL-1β, IL-6, IL-12, IFN-β, and TNF-α induced by MAP 0908 in BMDM at both translational and transcriptional levels." (PMID 29375563, 2017). "Infection with a single pathogen as well as super-infection with both pathogens increased IL-6 levels compared to mock-infected animals." (PMID 28195157, 2017). "Our results show a correlation between partial and complete protection against infection with the local secretion of high levels of IL-4, IL-6, IL-10, and IL-17." (PMID 29312230, 2017). "Taken together, these data indicate that infection of polarized colon epithelial cells with CMV VR1814 induces rapid (within 24 h) release of IL-6, which is able to significantly reduce the TER of the monolayer, thus diminishing epithelial barrier function." (PMID 28241080, 2017). "At onset of infection, serum levels of both pro- (TNFα, IL6, IL8) and anti-inflammatory (IL10) cytokines were significantly lower in SIRS-N compared to SIRS-P patients." (PMID 31058274, 2017). "Fbxo21-/- RAW264.7 cells demonstrated significantly impaired IL-6 and IFNβ production in response to LPS treatment, transfection of poly (I:C), poly (dA:dT) and poly (dG:dC), or infection with VSV and HSV-1." (PMID 27063938, 2016). "IL-6 exhibits a central role in host defense against infection and tissue injury, as well as in the progression of cancer malignancy." (PMID 27285760, 2016). "Infection of the epithelial cells with the efg1Δ/Δ cph1Δ/Δ mutant induced IL-6 and IL-1⍺ ~ 9 and 14 hours post-infection respectively." (PMID 27088599, 2016). "A significant increase of IL-6 in patients with VK247 infection was observed when compared to VK210 and mixed infections." (PMID 26943639, 2016). "At 26 h after infection clinical disease scores, serum cytokines (IL-6 and MIP-2), and vascular permeability in the liver were all significantly elevated in infected untreated animals compared with uninfected mice." (PMID 26872035, 2016). "Supernatants from FDCs cultures exposed to native and heat-inactivated viruses were collected at 10 days post-infection and the levels of IL-6 and IL-8 measured." (PMID 27596745, 2016). "In the acute infection model, IL-6 mRNA over-expression by both SM- and OM-HPBCs infected with S. aureus, as well as the weak responses in IL-1β and TNF-α mRNA expressions, were already observed during S. aureus and mesenchymal stem cell interaction." (PMID 27446812, 2016). "A1142 stimulated TNF-α and IL-6 secretion by mouse macrophage Raw 264.7 cells as detected at ~1 and ~6 h after infection." (PMID 27550826, 2016). "In summary, S. aureus induced low but statistically significant increases in mRNA expression of IL-6 in both SM- and OM-HPBCs and a small increase in IL-1β mRNA at 48 h post-infection in OM-HPBCs." (PMID 27446812, 2016).
infection (continued). "The gene expression of the two pro-inflammatory cytokines IL6 and TNFα was also highly significantly induced 30 h post infection in the E. coli treated and in the co-stimulated samples." (PMID 27310007, 2016). "CRP, a non-specific acute reactant protein of inflammation, is synthesized in hepatocytes and in response to release of cytokines, such as interleukin 6 release by monocytes and other immune cells under infection, tissue necrosis, and inflammatory disease." (PMID 27104127, 2016). "For splenocytes, the expression of IL-6 peaked at 6 h post-infection, with almost a 40-fold higher level compared to controls (p < 0.01)." (PMID 27852059, 2016). "IL-7 is involved in early T cell development and IL-6 is a pro-inflammatory cytokine involved in stimulating an immune response during infection." (PMID 27472318, 2016). "IL-6 is an important mediator involved in the regulation of the acute-phase response to injury and infection." (PMID 27867360, 2016). "Only infection with the tonB mutant was sufficient to induce more secretion of IL-6, CXCL1, or CXCL2 than infection with the entB ybtS tonB (siderophore-negative) mutant, indicating that all three siderophores are required for secretion of these cytokines." (PMID 27624128, 2016). "In the acute infection model, S. aureus induced an increase in IL-6 expression by SM-HPBCs that started at 6 h." (PMID 27446812, 2016). "IL-6 is a proinflammatory cytokine that is required at the time of infection and recruitment of cells to the inflammatory site." (PMID 27265209, 2016). "By contrast, treatment with anti-FasL helped macrophages to control infection and further increased macrophage activation, as assessed by IL-6 and NO production." (PMID 27195678, 2016). "IL-6 and TNFα are critical for rapid response to tissue injury and infections and induce the production of acute phase reactants in the liver whereas IL-12 is the main inducer of IFNγ in NK cells and T cells." (PMID 27548618, 2016). "We further show that reduced levels of type I interferon and IL-7 and elevated levels of IL-6, IL-8, IL-10 and VEGF strongly associated with severe disease both in primary and secondary infections." (PMID 26982706, 2016). "When compared with H7N9-CK or H7N9-HU, H5N1 induced significantly higher levels of IL-8 at 12 h post-infection; IL-8, IL-6, IL-10 and MCP-1 at 24 h post-infection; and IL-8, IL-6, IL-10, MCP-1 and TNF-α at 48 h post-infection." (PMID 26975414, 2016). "The IL-6 modulates the immune response to the initiation of detrimental infection and damage, and TNF-α, a pro-inflammatory cytokine derived from macrophages and monocytes, performs similar functions." (PMID 27501393, 2016). "Exposure of cells to heat-inactivated H. influenzae or P. aeruginosa caused significant release of the pro-inflammatory cytokines IL-6 and IL-8, as did infection with RSV alone." (PMID 27259950, 2016). "We also measured the production of pro-inflammatory cytokines TNF-alpha, IL-6 and KC at 2 h and 6 h post-infection both in the peritoneal washes and in blood samples." (PMID 27655040, 2016). "Analysis of infection-induced cytokines, including IL-8, IL-1β, IL-6 and TNF-α in vitro and in vivo revealed that cytokine and chemokine responses were dependent on expression of β-H/C that also elicited severe bladder neutrophilia." (PMID 27383371, 2016). "For PBLs at 3 and 6 h post-infection, the IL-6 levels were similar between infected and control groups." (PMID 27852059, 2016). "At 72 hours post-infection RSV-infected NHBE cells had increased expression of IL-6 (4.6-fold, p = 0.0220) and SDF-1 (2-fold, p = 0.0457) transcripts compared to mock infected cells." (PMID 27695127, 2016). "In contrast, the gingival epithelial cell line Ca9-22 does not respond to P. intermedia or T. forsythia infection with increased IL-6 secretion emphasizing the unexpected and obviously specific phenotype of the infection-responsive undifferentiated hDFSCs." (PMID 27974831, 2016).